CASP1 (caspase 1)
Diseases named in the same sentence as CASP1 in open-access papers (continued):
Sharing a sentence is not in itself a finding about the gene and the disease.
infection (continued). "Together, these results confirm that during L. mexicana infection in vivo, NLRP1-dependent caspase-1 activation of GSDMD, and subsequent pyroptosis control the neutrophil pool at the site of infection." (PMID 39250503, 2024). "Consistently, in Zbp1+/+ BMDMs, Caspase-1 was mildly activated following infection with PRV-WT, ΔVP22 (1–50 aa), or ΔVP22R but strongly activated upon infection with PRV-ΔVP22 and ΔVP22 (51–246 aa)." (PMID 39475237, 2024). "During primary infection of KSHV in endothelial cells, B cells in Kaposi’s sarcoma endothelial and primary effusion B-cell lymphomas can secrete IL-1β and IL-18 upon caspase-1 activation." (PMID 38177104, 2024). "DENV can facilitate the assembly of NLRP3 inflammasome during infection, which then regulates the cleavage of inactive pro-IL-1β (interleukin 1 beta, IL1B) via activating Caspase-1 (CASP1), a process that yields mature IL1B, thereby activating inflammation." (PMID 38355571, 2024). "Following the infection of IPEC-J2 cells with different doses of PEDV, the caspase-1 enzyme activity increased in a dose-dependent manner." (PMID 39728983, 2024). "As expected, in Zbp1+/+ BMDMs, Caspase-1 was mildly activated following infection with PRV-WT and PRV-ΔVP22R but strongly activated after infection with PRV-ΔVP22." (PMID 39475237, 2024). "At 4h post-infection, LV-NLRP12 cells showed elevated CASP1 and GSDMD cleavage, followed by higher levels of active IL−1β and IL-18." (PMID 39119293, 2024). "We observed that infection of CD18−/− BMDMs with the control strain induced lower levels of the cleaved form of caspase-1, IL-1β, and N-terminal Gasdermin D (N-GSDMD) compared to infection of WT BMDMs." (PMID 38724513, 2024). "We provide in vivo evidence that caspase-1 expression is critical for, IL-18 release, optimal interferon-γ (IFN-γ) production, monocyte and neutrophil recruitment to the site of infection, and parasite control." (PMID 39446964, 2024). "Levels of caspase-1 and ASC continued to increase long after patients had recovered from the infection." (PMID 37168848, 2023). "Upon infection or stimulation, NLRP3, ASC, and pro-caspase-1 assembles to form an inflammasome complex, which activates pro-caspase-1 by cleavage." (PMID 36726689, 2023). "Mechanistic studies using an in vitro human tonsil organoid infection model revealed that HIV infection of T cells also resulted in increased polyamine synthesis, which was dependent on the activities of caspase-1, IL-1β, and ornithine decarboxylase-1." (PMID 36693889, 2023). "Together, these data indicate that caspase-1, caspase-4, and caspase-5 are processed into their mature forms upon IFN-γ priming and infection with T4SS+ Lp." (PMID 37737612, 2023). "After WT W24 strain infection, NLRP3, caspase-1, GSDMD-N, and other factors in the classical pyroptosis pathway were found in the kidney, mainly in renal tubular epithelial cells." (PMID 36977062, 2023). "In this study, we found that the protein levels of the inflammasome signaling protein caspase-1, ASC, IL-1β and IL-18 were elevated during COVID-19 infection and remained elevated even after the active infection was over." (PMID 37168848, 2023). "We found that the Hsp90 inhibitor 17-DMAG can suppress macrophage cell death, active caspase-1, and GSDMD cleavage after SARS-CoV-2 GFP/ΔN infection." (PMID 37011862, 2023). "In WT macrophages, we observed PI incorporation after 4 h infection and this early cell permeabilization was GSDMD and Caspase-1/11-dependent and NLRP3 independent, suggesting that GSDMD cleavage occurs upstream to the NLRP3 inflammasome activation." (PMID 36828815, 2023). "Infection with HSV1 or F. novicida can induce AIM2-dependent and NLRP3/NLRC4-independent activation of CASP1, followed by the release of IL-1β and IL-18 and cell death." (PMID 36845112, 2023).
infection (continued). "Compared with WT BMDMs, the activation of CASP1/GSDMD/GSDME, CASP8/3/7, and RIPK3/MLKL in Mefv–/– and Zbp1–/– BMDMs decreased after infection with HSV1 or F. novicida, and completely inactive in Aim2–/– and Mefv–/–Zbp1–/– BMDMs." (PMID 36845112, 2023). "In MAPK and Caspase-1 pathways, the phosphorylation levels of ERK and P38 decreased in 15 min, 30 min, 60 min, and 120 min after infection with neutrophils by S. aureus Δlgt compared with S. aureus SA113." (PMID 37168122, 2023). "When infection and cellular injury occur, the NLRP3 inflammasome can activate caspase-1 and then induce the activation of the inflammatory cytokines IL-1β and IL-18." (PMID 36713830, 2023). "Infection of THP-1s with MVA induced a sharp increase in cell death, which was reversed by treatment with a caspase-1 inhibitor (VX-765) and, to a lesser extent, the pan-caspase inhibitor (zVAD-fmk)." (PMID 38065956, 2023). "At the same time, Nlrp3, Caspase-1, and GSDMD-N significantly increased after infection with PEDV, while GSDMD significantly decreased." (PMID 38132483, 2023). "During infection, the viral 3C protease cleaves NLRP1 between amino acids Q130 and G131, leading to inflammasome assembly, caspase 1 activation, inflammatory cell death, and cytokine secretion." (PMID 37508374, 2023). "Casp1–/– BMMs retain the ASC to caspase-8 pathway; and indeed, we observed weak caspase-8, BID, and caspase-3 cleavage at 4 hr post-infection (hpi), indicating that this pathway is relatively slow." (PMID 38055781, 2023). "Inhibited caspase-1 activation and IL-1β production in in vitro SARS-CoV-2 infection of primary human monocytes and reversed lung pathology in a mouse model of infection but increased the release of virus from macrophages." (PMID 36661317, 2023). "In conclusion, T.marneffei induces pyroptosis in hepatocytes through activation of the AIM2-caspase-1/-4-GSDMD axis, which may be an important cause of liver damage, and other death pathways including necroptosis and apoptosis may also be involved in the later stage of infection." (PMID 35639503, 2022). "The data show that IL-1β maturation as well as caspase 1 cleavage is abrogated in the NLRP3 knockdown PAMs, suggesting that inflammasome activation induced by ASFV-H240R infection depends on NLRP3." (PMID 36326277, 2022). "At 24 hr post infection, LDH levels in supernatant, cell viability (n=3) (G) and cleavage of GSDME, caspase-1, caspase-3, and caspase-8 were measured in ZIKV-infected JEG-3 cells." (PMID 35972780, 2022). "Collectively, ASFV-ΔH240R infection induced the activation of caspase 1 and the release of IL-1β from the ASFV-ΔH240R-infected PAMs, suggesting that the inflammasome is activated upon ASFV-ΔH240R infection." (PMID 36326277, 2022). "Peripheral blood CD4 T cells showed a modest increase of activated caspase 1 during acute SIV infection, which peaked on day 14 to a mean level of 5.5% following infection (P = 0.03 compared to day 0)." (PMID 36000842, 2022). "A recent study has also demonstrated that PA infection results in the activation of NLRP3 inflammasome in mice lungs, as indicated by induction of NLRP3 and ASC as well as caspase-1 and IL-1β." (PMID 36463179, 2022). "Together, these findings are consistent with a model where PMNs are the primary site of Caspase-1-dependent inflammasome activation and the production of IL-1 family cytokines during STM infection in the PMN-HIO model." (PMID 36191054, 2022). "Compared with WT mice, serum level of IFN-γ decreased dramatically in Casp1/11−/− mice on days 1 and 4 after PRU infection." (PMID 36214572, 2022). "During infection, flagella can elicit a strong NFkB-mediated activation of the host immune response via Toll-like receptor 5 (TLR5) and a caspase-1-mediated response via the Nod-like receptor Ipaf." (PMID 36557761, 2022). "We next quantified Caspase-1, Caspase-11 and Gasdermin D (GSDMD) cleavage by immunoblotting in wild-type (WT) BMDMs 12 hours post infection." (PMID 36318583, 2022).
infection (continued). "In the meantime, the inflammasome effectors including caspase-1, IL-1β, and GSDMD largely increased at infection; whereas IL-18 decreased during infection." (PMID 34161342, 2021). "We found the expressions of mRNA expression of caspase-1, GSDMD, caspase-3, MLKL, RIPK3, NLRP3, IL-1β and IL-18 and of proteins cleaved caspase-1, GSDMD, cleaved caspase-3 and pMIKL in the macrophages of the three infection groups to be upregulated (P<0.05)." (PMID 34513732, 2021). "Increased CASP1 and IFI16 gene expression is compatible with a role for pyroptosis, following the sensing of infection." (PMID 34753817, 2021). "To this end, our RT-PCR results were in agreement with the microarray data and we observed differential expression of caspase-1, caspase-4, and caspase-8 and NLRP3 in MDR-PA induced infection." (PMID 35046947, 2021). "NLRP3 inflammasome activation impaired agonist- or infection-induced TLR signaling and cytokine production through the proteolytic cleavage of MyD88 by caspase-1." (PMID 35069570, 2021). "To define which pathway was required for XWK4-activated inflammasome activation, we analyzed caspase-1 activation in Ifnar–/– and Ifnar–/–Ifnγ–/– double knockout (AG6) BMDMs in response to XWK4 infection." (PMID 34869331, 2021). "Consistent with previous studies, caspase-1/11 and GSDMD were required for host protection against infection at this infectious dose." (PMID 34154417, 2021). "Under a low degree of infection, NAIP5 recruits NLRC4 and pro-caspase-1 to form a complex to relieve autophagy inhibition, and induce cell protection." (PMID 33644066, 2021). "In this study, inflammasome pathway analysis showed that infection with virulent strains of T. cruzi leads to high increase in the expression of NLRP3, caspase-1 and IL-1β in the myocardium." (PMID 34336720, 2021). "Macrophages infected with B. thailandensis undergo NLRP3-, NLRC4-, caspase-1-, caspase-11-, and GSDMD-dependent pyroptosis (52, –, 60), but the role of other cell death pathways during infection is poorly understood." (PMID 34154417, 2021). "At 3 h post-infection, the relative expression of ASC and caspase-1 mRNA in the HPI infection groups was higher than that at the other time-points." (PMID 33678162, 2021). "We next examined RhoA-GTP levels in Aim2–/–, Asc–/– and Casp1–/– BMDMs during HSV1 and F. novicida infections." (PMID 34471287, 2021). "Western blot analysis of the cell lysates combined with the cell culture supernatants (total) demonstrate that infection with SS−/− mutants led to decreased cleavage of GSDMD, CASP1, and IL-1β." (PMID 33441602, 2021). "At all time point post-infection, the positive cell rate of NLRP3 and caspase-1 in the HPI infection groups were significantly higher than those in the control group (P < 0.01)." (PMID 33678162, 2021). "HPI+/HPI−-infection was accompanied by upregulated expression levels of NLRP3, ASC, caspase-1, IL-1β, IL-18 and GSDMD, with significantly higher levels detected in the HPI+ group compared to those in the HPI− group (P < 0.01 or P < 0.05)." (PMID 33678162, 2021). "T. gondii infection time-dependently induced NLRP3 and ASC protein expression, adequately induced NLRP6 and cleaved caspase-1 expression, and moderately induced NLRC4 expression at 4 h post-infection." (PMID 33712075, 2021). "Of several inflammasome complexes known to activate caspase-1, the most commonly evaluated is the NLRP3 inflammasome, which is a multiprotein platform that is activated upon cellular stress or infection." (PMID 33839695, 2021). "Collectively, these findings demonstrate that the host mounts an initial immune response to S. aureus craniotomy infection that is TLR2- and caspase-1-dependent, with IL-1β being a key player." (PMID 32290861, 2020). "C57BL/6J mice were injected intradermally with 5448, 5448AP or saline and euthanised at 6 or 24 hours post-infection, with neutrophil populations (CD45+/CD11b+/Ly-6G+), caspase-1 activation and CD16 expression characterised by flow cytometry." (PMID 33585270, 2020).
infection (continued). "After infection, THP1 macrophages were fixed and stained using immuno-fluorescence labelling against NLRP3 and caspase-1 for visualization by widefield fluorescence microscopy." (PMID 32230726, 2020). "To examine how development of NLRP3 inflammasomes was affected by infection with P. gingivalis or S. mitis, we measured the expression of NLRP3, CASP1, and ASC at 1, 2, 6, and 24 h (MOI = 50) time points." (PMID 32903638, 2020). "The effector caspase-1 cleaves interleukin (IL)-1β, IL-18, and gasdermin D (GSDMD), resulting in cytokine release and the induction of pyroptotic cell death to eliminate infections and restore homeostasis." (PMID 32962268, 2020). "This was in agreement with our finding that the pro-apoptotic genes CASP1, CASP4, and CASP7 were increased during infection." (PMID 32093375, 2020). "The residual caspase-1/11, ASC-dependent and NLRP3/AIM2-independent maturation of IL-1β in response to infection with H37Rv and isolate 411 suggests the involvement of an additional inflammasome sensor in detecting these bacteria." (PMID 32111888, 2020). "It has been demonstrated that severe infection injury can promote the activation of NLRC4 as well as NLRP3 inflammasome, regulate the activation of Caspase-1, and eventually lead to inflammatory injury." (PMID 33489931, 2020). "Consistent with a temporally early role of caspase-4 in EPEC-induced pyroptosis, immunoblots showed caspase-4 activation in cell lysates within 1 h of infection, whereas cleaved caspase-1 and GSDMD proteins were detected at 3 and 5 h post-infection." (PMID 31018119, 2019). "The NLRP3-ASC-caspase-1 inflammasome rapidly processed cytokines and GSDMD following infection by virulent EPEC." (PMID 31018119, 2019). "Infection with dengue virus results in NLRP3 inflammation, caspase-1 activation, and caspase-1-dependent IL-1β secretion." (PMID 31316518, 2019). "In contrast, infection with the less-virulent HSV-1 strains (KOS, RE or F) or with the clinical isolate KOS63 induced less FLICA confirming a lower Caspase-1 activation by the less-virulent strains." (PMID 31367214, 2019). "To determine the role of caspase-1 and NLRP3 in IL-1β secretion by B. abortus-infected LX-2 cells, we performed the infection of LX-2 cells in the presence of specific pharmacological inhibitors." (PMID 32038610, 2019). "Infection by DENV2(NGC) resulted in the activation of IL-1β secretion, Casp-1 p20 maturation, IL-1β p17 processing, and DENV2 NS3 production." (PMID 31824450, 2019). "To test this we measured CASP7 cleavage in response to infection of C57BL/6 and Casp1/11–/–macrophages." (PMID 31251782, 2019). "After infection, HMGB1 is released into the extracellular space, which is required for the activation of the inflammasome and the caspase 1 activation." (PMID 31049022, 2019). "Following H37Rv infection, we found increased levels of mature CTSB, cleaved caspase-1, and mature IL-1β from infected macrophages, the latter observation confirming that the changes in IL-1β levels measured by ELISA reflect alterations in the mature cytokine." (PMID 29977244, 2018). "Caspase-11 was efficiently upregulated in response to infection with B. abortus in C57BL/6 and Casp1-/-Casp11Tg BMDMs." (PMID 30589883, 2018). "Taken together, these data showed that infection of THP-1 cells with GRA15-intact T. gondii produced IL-1β in a manner dependent on NLRP3 and caspase-1; this led to an indirect reduction in IDO1 proteins, thereby supporting parasite growth in human cells." (PMID 30301855, 2018). "During HIV abortive infection, the engagement of the interferon-gamma-inducible-protein 16 (IFI16) in response to cytosolic viral DNA leads to inflammasome assembly and caspase-1 mediated CD4 T cells pyroptosis in lymphoid tissues." (PMID 30459758, 2018). "Combined treatment with YVAD-CHO caspase-1 inhibitor and PGE2 before infection with Y. enterocolitica led to a decreased IL-1β secretion as expected." (PMID 30429830, 2018).
infection (continued). "We found that mPDCA-1-mediated depletion of pDCs in Aim2−/−, Nlrp3−/−, Casp1−/−, and Il1r1−/− mice markedly decreased serum levels of IFN-α/β at day 1 after YM infection, compared with those treated with control antibody." (PMID 30470758, 2018). "To validate that NLRP6 induces pyroptosis, we assessed the expression of caspase-1 and gasdermin-D in BMDMs from WT and NLRP6 KO mice after infection with S. aureus (MOI of 20) for 8 hours." (PMID 30248149, 2018). "In contrast, Nlrp3−/−, Casp1/11−/−, and Asc−/− mice had diminished numbers of activated CD8+ CD9+ T cells at 2 and 4 weeks that were totally abolished at 10 weeks of infection." (PMID 28740491, 2017). "Total RNA was collected at 24 hours post infection for the detection of the transcript levels of NLRP3, caspase 1, IFNα and IFN inducible genes." (PMID 29167459, 2017). "From 2 to 10 weeks of infection, increased frequencies of IFN-γ+ and IL-17+ CD4+ T cells were seen in the lungs of WT mice when compared with Nlrp3−/−, Casp1/11−/−, and Asc−/− mice." (PMID 28740491, 2017). "Our findings demonstrated that the genetic deficiency of NLRP3, Casp1/11, and Asc totally impaired the expression of IL-1β, IL-18, NLRP3, Casp1, and ASC mRNA in the lungs of infected mice at week 4 of infection." (PMID 28740491, 2017). "We, for the first time, have shown that infection with South American (PRVABC59) or Nigerian (IBH30656) strains of ZIKV activated NLRP3 and caspase 1 in monocytes." (PMID 29167459, 2017). "When infection initiates, NOD-like receptors (NLRs) are able to assemble a multiprotein complex (inflammasome), which activated caspase-1 and even induced pyroptotic." (PMID 29184853, 2017). "We have further studied the expression of intracellular pro-IL-1β, IFN-γ, IL-4, IL-17, and TGF-β cytokines by CD4+ and CD8+ T cells in the lungs of infected WT, Nlrp3−/−, Casp1/11−/−, and ASC−/− mice at 48 h, 2, 4, and 10 weeks of infection." (PMID 28740491, 2017). "The activation of caspase-1 and IL-1β production induced by SEA in infected HSCs was measured at various time points after the start infection." (PMID 28808303, 2017). "A statistically significant increase in percentage of ASC specks (exposed to 3 h LPS followed by 3 h infection), and FLICA (caspase-1 active) and propidium iodide (PI) double-positive (pyroptotic) cells in WT vs. WAS KO BMDCs was also recorded." (PMID 29146903, 2017). "At day 3 post-infection, although limited, PMN death was evident and comparable between wildtype, Asc-/-, and Casp1/11-/- mice, but reduced in Nlrp3-/- mice as assessed by 7-AAD staining." (PMID 27926940, 2016). "The results of this study demonstrate that HGPg infection not only induces NLRP3 upregulation, but also enhances active caspase-1 and mature IL-1β expression in HGFs." (PMID 28083517, 2016). "Caspase-1 and Caspase-3 levels in the CD4High group increase robustly in acute HIV infection and the infection is soon under control." (PMID 25806508, 2015). "The importance of Caspase-1 in defense against SPN varies greatly depending on model, mirroring the variable role of IL-1 in these infections." (PMID 26500655, 2015). "We first examined the number of formed active caspase-1 foci in the uninfected (UI), TOE-A5-infected, and TOE-A5/nleA-infected dTHP-1 cells at 3 and 6 hrs post-infection." (PMID 26332984, 2015). "We found that under conditions where SPI-1 is downregulated (in vivo infection and in vitro stationary growth phase), both NLRC4- and NLRP3-caspase-1-dependent pathways were activated." (PMID 25879288, 2015). "In one previous study, infection by S. typhimurium resulted in NLRC4- and caspase-1-dependent secretion of IL-1α." (PMID 25071770, 2014). "In serum 24 hours after infection, TNF-α, MIP-2, and Il-1β levels were low but KC was readily detectable and higher in Nlrc4−/− mice compared to Casp1−/−Casp11−/− mice." (PMID 25232720, 2014).